RN7SKP107 (RN7SK pseudogene 107)
Gene: Miscellaneous RNA gene on chromosome 14 (89,621,918 to 89,622,207, forward strand). Ensembl gene ENSG00000201027.
Homologues: Orthologues: chimpanzee 7SK (94% identical). Paralogues in human: RN7SKP71 (79% identical), 7SK (78% identical), RN7SKP9 (78% identical), RN7SKP255 (77% identical), RN7SKP246 (77% identical), RN7SKP90 (77% identical), RN7SKP133 (77% identical), RN7SKP180 (77% identical), RN7SKP176 (76% identical), RN7SKP243 (76% identical), RN7SKP128 (76% identical), RN7SKP161 (76% identical), and 284 more.